LIN28B (lin-28 RNA binding posttranscriptional regulator B)
Diseases named in the same sentence as LIN28B in open-access papers (continued):
Sharing a sentence is not in itself a finding about the gene and the disease.
cancer (continued). "The shRNA-knockdown cell lines A2780 and TOV-112D were challenged with camptothecin, which is a common way to induce apoptosis in cancer cells, to evaluate the contribution of LIN28B to apoptosis." (PMID 30174831, 2018). "Activation of Lin28B expression in cancer cells can be triggered by upstream transcriptional factors, such as c-Myc and NF-κB." (PMID 29301498, 2018). "Overexpression of LIN28A/LIN28B that results in dysregulation of let-7 microRNAs are essential pathological events in tumorigenesis and progression of many human cancers." (PMID 28400788, 2017). "In the present study, Lin28B expression was not only markedly upregulated in human PDAC tissues but was also well correlated with cancer metastasis and a poor prognosis." (PMID 28947981, 2017). "The different distribution patterns of Lin28B in cancer cells and its mechanisms should be examined in more detail in the future." (PMID 28947981, 2017). "Aberrant regulation of the Lin28B and let-7 loop in human malignancies is reportedly involved in cancer development, contributing to cell transformation, metastasis, resistance to cell death, metabolic reprogramming, and tumor-associated inflammation." (PMID 28947981, 2017). "In another study, LIN28B was found to link molecularly inflammation and cancer via a positive feedback loop involving NF-κB activation and derepression of the let-7 regulated gene IL-6." (PMID 28400788, 2017). "Lin28/Lin28B and the let-7 family have recently been shown to exert opposite roles in many cellular processes, particularly in cancer development and progression." (PMID 28947981, 2017). "Lin28B expression was not only markedly upregulated in human PDAC tissues but was also well correlated with cancer metastasis and a poor prognosis." (PMID 28947981, 2017). "The results indicate that Lin28B is the highest upregulated cancer stem cell factor by mH2A1 depletion in LD611 cells." (PMID 26028027, 2016). "Because the induction of Lin28B inhibits the expression of mature let-7 miRNAs, we investigated the expression of mature miRNAs that are known to be involved in the cancer regulation after mH2A1 depletion." (PMID 26028027, 2016). "These researches imply the importance to distinguish the expression and functions of both Lin28A and Lin28B in certain cancer types." (PMID 27793004, 2016). "Because Lin28B has been well characterized as a positive regulator of cancer progression and invasion in several types of cancers, we selected Lin28B as the putative target gene of mH2A1 on the regulation of stem-like properties." (PMID 26028027, 2016). "Lin28B was identified as a novel downstream target gene of mH2A1 from the human cancer stem cell marker PCR arrays, indicating that Lin28B is upregulated by mH2A1 depletion." (PMID 26028027, 2016). "Although it was demonstrated that either Lin28A or Lin28B is over-expressed in malignant tumors and promotes cancer progression, few researches detected the expression and function of both oncogenes in human malignant tumors at same time." (PMID 27793004, 2016). "It is featured by c-Myc oncoprotein and Lin28B overexpressions and cancer progenitor-like cell formation in the liver." (PMID 27713163, 2016). "It has shown that the biogenesis of let-7a was blocked by overexpression of c-Myc/Lin28B axis in cancer cells." (PMID 26893968, 2016). "Recently, our study demonstrated that hepatic premalignant alterations appeared in canines after a 10-day AAI oral administration, featured by c-Myc oncoprotein and Lin28B overexpressions and cancer progenitor-like cell formation." (PMID 27713163, 2016). "Several lines of evidence indicate that Lin28B is an important regulator of growth and metabolism in stem cells and is critical for the formation of cancer stem cells, and contributes to tumor aggressiveness and spread." (PMID 27248826, 2016). "The LIN28B protein shows cell cycle‐dependent nuclear translocation, and its overexpression can promote cancer cell proliferation." (PMID 27021521, 2016).
cancer (continued). "In contrast to the expression of LIN28A/LIN28B proteins, the expression of let-7 family miRNAs is typical decreased in cancers." (PMID 26123544, 2015). "Collectively, these findings have provided strong evidence that LIN28B is a bona fide oncogene mediating cancer initiation and progression, and also a novel therapeutic target against cancer." (PMID 26478718, 2015). "Previous findings have indicated that LIN28B is usually overexpressed in a broad spectrum of human cancers and is critically required for cancer overgrowth." (PMID 26478718, 2015). "LIN28A and LIN28B are stem cell factors that regulate thousands of RNAs and are expressed in aggressive cancers." (PMID 25638158, 2015). "Because a line of evidence has revealed that LIN28B alone is capable to induce cell transformation in vitro and sufficient to initiate multiple cancers in vivo." (PMID 26478718, 2015). "The RBP LIN28A/LIN28B, a direct target of the let-7 family of miRNAs, is an inhibitor of let-7 biogenesis and is frequently up-regulated in cancers." (PMID 26123544, 2015). "Taken together, our findings supported the notion that Lin28B is expressed in cancer stem cell-like subpopulations." (PMID 24244607, 2013). "Since Lin28 is known to be a marker for stem cells, we predicted Lin28B is also related to cellular stemness and is potentially a marker for cancer stem cells." (PMID 24244607, 2013). "Results showed that Lin28B promoted cancer cell migration, invasion, palate colony formation and in vivo tumour proliferation." (PMID 24386298, 2013). "In conclusion, we identified Lin28B as a potential circulating oncofetal cancer-stem-cell-like marker in predicting the recurrence of HCC." (PMID 24244607, 2013). "Further, it was reported that the stable Lin28B expression in FaDu cells (one of the head and neck cell lines) can enhance cell survival in stress conditions and promote cancer relapse." (PMID 24386298, 2013). "The LIN28A homologue LIN28B promotes tumorigenicity in liver, ovarian, and colon progenitors and cancer cell lines." (PMID 23846349, 2013). "In conclusion, the oncofetal gene Lin28B is a potential oncofetal cancer-stem-cell-like circulating tumor cell marker that correlates with HCC recurrence after hepatectomy." (PMID 24244607, 2013). "For screening possible Lin28B expression in different tumor types, RT-PCR was performed in various human cancer cell lines." (PMID 24244607, 2013). "Over-activation of LIN28A or LIN28B is one mechanism by which cancer cells can eliminate let-7 microRNAs and allow for increased expression of pro-oncogenic signals." (PMID 23846349, 2013). "The carcinoma cells at the invasive front tended show strong staining for Lin28 and Lin28B compared with those in other areas." (PMID 22433967, 2012). "Despite the prominent role of LIN28B in development and cancer, the mechanisms of its transcriptional regulation are largely unknown." (PMID 38704454, 2024). "Interestingly, the expression of LIN28A and LIN28B is mutually exclusive in many human cancer cell lines." (PMID 38976670, 2024). "Mechanistically, Lin28B repression is accompanied by SOX6 physical binding within its locus, suggesting a direct mechanism of LIN28B downregulation that might contribute to the fetal/adult erythropoietic transition and restrict cancer proliferation." (PMID 38704454, 2024). "Similarly, the tumor suppressor let-7-5p family members play an important modulatory role in multiple human cancers including HCC by repressing oncogenic targets such as EGFR/LIN28B/ HMGA2 and C-MYC that are all important players in oncogenesis." (PMID 38256049, 2024). "Furthermore, these LIN28B targets promote cancer initiation through an increase in protein synthesis." (PMID 38875287, 2024).
cancer (continued). "Indeed, a previous study also showed interactions between LIN28B and general protein synthesis machinery in cancer." (PMID 38875287, 2024). "However, LIN28B has been shown in other cancers to bind the 3′ UTR of oncogene mRNA transcripts, increasing their stability and, accordingly, their translation." (PMID 37370851, 2023). "Additionally, numerous studies in these cancer entities support the important role and effects of LIN28B in the context with tumor growth and metastasis formation." (PMID 37304235, 2023). "Moreover, the reduction in mRNA levels of MYCN and stemness-related transcription factors in cancer stem-like cells that was impaired by upregulated ADAMTS9-AS2 expression was rescued by overexpressing LIN28B." (PMID 37991019, 2023). "Since ectopic expression of LIN28B in other cancers usually correlates with cancer stem cell-like properties and poor prognosis, our data provide supporting evidence for investigating the potential roles of LIN28B in the CCA context." (PMID 34548635, 2022). "Additionally, lin28B promotes cancer cell migration and cancer progression, metastasis, and recurrence among colorectal cancer patients." (PMID 36057607, 2022). "LIN28A/LIN28B are LIN-28 family members that are associated with the developmental timing and self-renewal of embryonic stem cells, and their aberrant expression is related to cancer progression." (PMID 35654793, 2022). "Indeed, a comprehensive analysis of Lin28A and Lin28B expression over a panel of 527 human cancer cell lines revealed that the paralogs are overexpressed in roughly 15% of cancer types." (PMID 36230562, 2022). "However, lin28B has demonstrated more frequent upregulation and a close relationship with various human cancers." (PMID 36057607, 2022). "While we could not detect LIN28A-stained cells in either tumour or normal tissue, heterogeneous LIN28B protein expression in a subpopulation of cancer cells was found in 3 CCA patient tissues." (PMID 34548635, 2022). "It is possible that LIN28B could enhance cancer transformation in premalignant cells from other insults." (PMID 34548635, 2022). "Interestingly, a recent study showed that Lin28B interacted with DIS3L2 in the cytoplasm of Lin28B-expressing cancer cell lines, suggesting that it was also involved in a TUTase-dependent pathway." (PMID 36008964, 2022). "LIN28B was activated in multiple types of cancer cell lines." (PMID 35780125, 2022). "Although we observed LIN28B expression in only a small subpopulation of cancer cells, reactivation of LIN28B may account for intratumour functional heterogeneity within CCA, and a positive subset of CCA is likely to have more metastatic potential." (PMID 34548635, 2022). "It is still unclear whether LIN28B alone is sufficient to induce cancer transformation of normal adult cholangiocytes." (PMID 34548635, 2022). "In contrast to the localization pattern observed in certain cancer cells, in which LIN28B is more likely to be detected in the nucleus whereas LIN28A localizes to the cytosol, the two paralog proteins appear to localize both in the nucleolus and the cytosol in pluripotent stem cells." (PMID 34331666, 2022). "Lin28B and Let-7c also participate in other kinds of cancers." (PMID 36057607, 2022). "Lin28A and Lin28B are mutually exclusive in expression in human cancer cell lines." (PMID 36230562, 2022). "In summary, we explored a breakthrough function of Lin28B in the management of the pre-metastatic niche by decreasing immune surveillance, which is an extremely important prerequisite for the survival and rapid growth of incoming cancer cells." (PMID 35173168, 2022). "Both Lin28A and Lin28B play important roles in cancer development and progression." (PMID 36230562, 2022).
cancer (continued). "Our work demonstrates that LIN28B promotes many cancer stem cell-like properties in CCA." (PMID 34548635, 2022). "In addition, we demonstrated previously that LIN28B acts as an oncogene in genetic mouse models of colorectal adenomas and cancers, which was corroborated subsequently by others." (PMID 33755595, 2021). "Considering that LIN28B may potentially promote cancer stem-like properties, chemotherapeutic resistance in cholangiocytes by enhancing ALDH activity." (PMID 34837926, 2021). "Moreover, cancer stem cells (CSCs) were one essential reason of cancer progression and chemoresistance, and LIN28B was shown to be the highest gene in CSC-like cells." (PMID 34353342, 2021). "This specific expression pattern together with its de–regulation and functional role in a set of human cancers puts MSI1 in row with other bona fide oncofetal RBPs such as IGF2BP1 and 3, LIN28B or MEX proteins, representing diagnostic markers with therapeutic potential for cancer treatment." (PMID 34062997, 2021). "Other interesting examples included AGO4, LIN28A and SMAD2 overmutated in BLCA (an otherwise extremely low-mutation cancer with no mutations in other genes); LIN28B overmutated in SKCM; PRKRA overmutated in OV; and DDX5 overmutated in BRCA and KIRP." (PMID 33406242, 2021). "Furthermore, Lin28B is a promising target for cancers, and the development of such simplified siRNA analogs, possibly together with novel targeting units, holds potential." (PMID 32311310, 2021). "We identified and characterized over 3600 somatic mutations in 29 miRNA biogenesis genes and showed that some of the genes are overmutated in specific cancers and/or have recurrent hotspot mutations (e.g. SMAD4 in PAAD, COAD and READ; DICER1 in UCEC; PRKRA in OV and LIN28B in SKCM)." (PMID 33406242, 2021). "Indeed, a number of studies have shown that RBPs, including LIN28B, promote tumorigenesis in diverse cancer types." (PMID 33755595, 2021). "In addition, we previously showed that Lin28B, a prominent oncoprotein, is a key factor for the maintenance of cancer stem cells and a main driver in the development of prostate cancer." (PMID 32311310, 2021). "Furthermore, Lin28B is a promising target in different cancers, and the development of new siLin28B analogs, possibly in conjunction with novel targeting units, holds great potential for future antitumor therapies." (PMID 32311310, 2021). "LIN28B is an RNA-binding protein known as an emerging oncogenic driver in several cancers." (PMID 32528950, 2020). "This study suggested that the exosomes derived from local cancer cells could promote the construction of distant metastases through transferring the exosomal protein Lin28B to metastatic cancer cells." (PMID 31413760, 2019). "Overexpression of Lin28A or Lin28B suggests poor prognosis for cancer patients." (PMID 30976203, 2019). "In addition, LIN28A and LIN28B are upregulated in several advanced human cancers and are reliable predictors of a poor prognosis." (PMID 31147574, 2019). "Most importantly, we demonstrated that the PCAF-mediated acetylation of Lin28B might de-repress the processing of let-7a-1 and let-7g, and these findings shed light on the potential application of acetylated Lin28B for future cancer therapy." (PMID 29301498, 2018). "Lin28B is currently known to be involved in the promotion and development of tumors, thus indicating that it may be a potential target in human cancer therapy." (PMID 29301498, 2018). "The expression of Lin28B in cancer cells can be activated by transcription factors and epigenetic modifiers, such as Myc, NF-κB and Sirt6; however, much of the underlying mechanism remains unclear." (PMID 29301498, 2018). "The LIN28/let-7 pathway is directly implicated in cancer using genetically engineered mouse models where ectopic LIN28A and/or LIN28B expression cause and/or enhance progression of neuroblastoma, Wilms tumor, mast cell leukemia, hepatocellular carcinoma, and colorectal adenocarcinoma." (PMID 30057901, 2018).
cancer (continued). "We further investigated the potential mechanisms by which Lin28B accelerates cancer metastasis." (PMID 28947981, 2017). "More importantly, concomitant treatment with statins and the NF-κB inhibitor (CAPE) synergistically induced anti-cancer activities including the attenuation of proliferation and growth along with downregulation of LIN28B and cyclin D1, and restoration of let7-miRNA expression in human CRPC cells." (PMID 28910332, 2017). "Activation of either LIN28A or LIN28B, two highly related RNA binding proteins (RBPs) and proto-oncogenes, is responsible for the global post-transcriptional downregulation of the let-7 microRNA family observed in many cancers." (PMID 28400788, 2017). "Emerging evidence indicates that LIN28B is an oncogenic driver in cancer stem cells." (PMID 28404969, 2017). "Both Lin28a and Lin28b are misexpressed in a number of tumor and cancer cells." (PMID 27881476, 2017). "In addition, both genetic and epigenetic events contribute to LIN28B expression in a subset of cancers." (PMID 28400788, 2017). "Emerging evidence have suggested LIN28B in contributing to the transformation of cancer stem cells." (PMID 28693523, 2017). "This indicates that caffeine could be of great therapeutic value via targeting the carcinogenic and metastatic Lin28B/Let-7b axis in active breast stromal fibroblasts and also inhibits the link between inflammation and cancer." (PMID 27248826, 2016). "Numerous studies have shown that both Lin28A and Lin28B are over-expressed in many cancer types." (PMID 27793004, 2016). "Moreover, disruption of this RING finger motif resulted in abrogation of proliferation and invasion of cancer cells in which Lin28B-let-7-HMGA2 signaling is conserved." (PMID 27821801, 2016). "Moreover, in addition to Lin28B there are several putative cancer stem cell markers, such as MUC1, CD38, FLOT2, EGF and IKBKB that were also upregulated (signal log2 ratio>0.5) in mH2A1-depleted LD611 cells." (PMID 26028027, 2016). "Lin28B also directly binds and inhibits the processing of the miRNA let-7 which can also target c-Myc and other transcripts for degradation and is commonly repressed in human cancers." (PMID 27007052, 2016). "Additionally, RNA binding protein Lin28A and Lin28B interacts with different target mRNAs in cancer cells." (PMID 27793004, 2016). "Interestingly, however, a recent study showed that LIN28B interacts with DIS3L2 in the cytoplasm of LIN28B-expressing cancer cell lines, indicating that it also participates in the TUTase-dependent pathway." (PMID 26399619, 2016). "However, one recent research showed that Lin28B is exclusively located in the nucleus, and some other studies demonstrated that Lin28B predominantly distributes in the nucleus of certain cancer cells." (PMID 27793004, 2016). "Recent studies suggest that the LIN28A/LIN28B and let-7 loop may also regulate cancer cell immune evasion." (PMID 26123544, 2015). "Its upregulation correlates with aggressive clinicopathological parameters and adverse prognosis, thus suggesting that LIN28B might serve as a novel cancer biomarker as well as therapeutic target for OSCC." (PMID 26478718, 2015). "This is well consistent with the oncogenic roles of LIN28B driving cancer initiation." (PMID 26478718, 2015). "By using an expressed sequence tag bioinformatic algorithm, we identified that Lin28 homolog B (Lin28B) may have an oncofetal expression pattern which may facilitate detecting cancer cells in adults." (PMID 24244607, 2013). "Lin28B staining was also predominantly detected in the nuclei of cancer cells." (PMID 22433967, 2012). "circHIPK3/miR-107/LIN28B axis may be a mechanism of chemoresistance in gastric and ovarian cancers." (PMID 40061896, 2025).